TIGIT (T cell immunoreceptor with Ig and ITIM domains)
Diseases named in the same sentence as TIGIT in open-access papers (continued):
Sharing a sentence is not in itself a finding about the gene and the disease.
tumor (continued). "The outer membrane protein Fap2 derived from Fusobacterium nucleatum directly binds to the inhibitory receptor T cell immunoreceptor with immunoglobulin and ITIM domain (TIGIT) on NK cells and tumor-infiltrating T cells and abolishes their activity, thus enhancing tumor-immune evasion." (PMID 38741166, 2024). "Additionally, through immunohistochemical staining of tumor tissues, the expression levels of immune checkpoints such as PD-L1, TIGIT, and NKG2A can be detected." (PMID 39559360, 2024). "At the same time, a variety of tumor-associated Trm cells also exhibit phenotypes similar to those of depleted T cells, including upregulation of a series of immune checkpoints, such as TIM-3, LAG-3, PD-1 and T-cell immune receptor (TIGIT)." (PMID 38779662, 2024). "TIGIT was expressed in a few CAR T cells before the first stimulation with STEAP1+ tumor cells." (PMID 38203757, 2024). "TIGIT has shown potential in enhancing anti-tumor immunity in the treatment of HCC." (PMID 39796695, 2024). "TIGIT is a CD8 + effector memory T cell inhibitory molecule that interacts with PVR to inhibit anti-tumor immune responses, and PVRL1/TIGIT inhibitors and anti-PD1 antibodies could be developed to treat HCC52." (PMID 38890507, 2024). "TIGIT, an immune checkpoint receptor, serves as an inhibitor of anti-tumor immune responses." (PMID 38438420, 2024). "Over-expressed TIGIT in tumor-infiltrating NK cells in solid tumors was reported to be prognostic." (PMID 39457520, 2024). "Similar results were obtained with this combination approach in a B16 melanoma mouse model, where NK cell-specific TIGIT-deficiency resulted in the upregulation of DNAM-1 (CD226) expression by tumor-infiltrating NK cells and in tumor growth inhibition in CD155-deficient mice." (PMID 39339180, 2024). "Many recent reports, especially in the field of tumor immunology, have investigated the expression of the immune checkpoint molecules TIGIT, CD226 and CD155 and their possible role in immune regulation, while fewer papers have been published in the context of pregnancy." (PMID 38326745, 2024). "Similarly, we also found that tumor-infiltrating γδ T cells expressed high levels of co-inhibitory molecules, PD-1 and TIGIT." (PMID 38321065, 2024). "Aspirin may suppress the expression of TIGIT on T cells and Regulatory T cells (Tregs) and inhibit T cell viability, and therefore induce tumor cell apoptosis." (PMID 39113892, 2024). "The poliovirus receptor (PVR or CD155), a member of the adhesion molecule family, serves as a ligand for TIGIT and is highly expressed on the surface of various tumor cells, inhibiting the activation of T and NK cells, thus promoting tumor metastasis and progression." (PMID 38291470, 2024). "Additionally, TIGIT promotes NK cell-dependent tumor immunity, as demonstrated in diverse mouse models." (PMID 38342925, 2024). "TIGIT is mainly expressed on tumor-infiltrating effector T cells, regulatory T cells, and NK cells within various tumor types, and exerts its immunosuppressive effects in T cells by competing with the CD226 receptor for binding to the shared ligands CD155 and CD112." (PMID 39409893, 2024). "Elevated intra-tumor levels of TIM-3 have also been associated with the suppression of T-cell responses and reduced production of TNF-α, IFN-γ, and GrzB, especially when co-expressed with TIGIT, CTLA-4, or LAG-3." (PMID 38891056, 2024). "TIGIT contributes to tumor immune evasion through various immunity mechanisms, including inhibiting NK cell-mediated cytotoxicity, suppressing T-cell proliferation, restricting CD8+ T cell activation in the TME, and promoting inflammatory CD4+ T cell responses to impede tumor apoptosis." (PMID 38627681, 2024). "The combined inhibition of the TIGIT and PD-1/PD-L1 signaling pathways can also lead to the synergistic enhancement of the proliferation and function of anti-tumor CD8+ T cells, thus boosting anti-tumor efficacy and ultimately improving overall patient survival." (PMID 38627681, 2024).
tumor (continued). "The phenomenon of “exhaustion” is the consequence of a chronic stimulation of T cells by tumor cells that lead to the upregulation of immune checkpoint markers such as PD-1, LAG-3 and TIGIT on T cells, rendering TILs inadequate at exerting an effective anti-tumor immune response." (PMID 39594814, 2024). "However, it is worth mentioning that the expression of the immune checkpoints PDCD1, LAGLA3, and TIGIT is higher in tumor-specific Trm cells than in Tcm cells or Tem cells." (PMID 38779662, 2024). "In the TME, TIGIT is frequently co-expressed on tumor-infiltrating lymphocytes (TILs), particularly in concert with other immune checkpoint molecules such as PD-1, lymphocyte activation gene-3 (LAG-3), and T-cell immunoglobulin and mucin-domain containing-3 (TIM-3)." (PMID 39152301, 2024). "Blockade of TIGIT and other immune checkpoints relies on the activated immune cells to eradicate tumors, which means that tumor-infiltrating lymphocytes (TILs) play a pivotal role in this process, thereby limiting the applicability of this therapy in immunosuppressed patients and ‘cold’ TME." (PMID 39771968, 2024). "We also found that GFI reduced the mRNA and protein expression of TIGIT in the tumor tissues." (PMID 38169590, 2024). "Preventing TIGIT signaling through the use of anti-TIGIT ICIs may restore immune responses in tumor cells." (PMID 38451273, 2024). "Treatment with anti-PD-L1 + mIgG2a anti-TIGIT antibodies increased the proportion of gp70-specific CD8+ T cells in the tumour and drove those cells to downregulate TOX while upregulating TCF1, consistent with a shift from exhausted effector cells towards a more memory-like state." (PMID 38418879, 2024). "Inhibition of both the TIGIT and PD-1/programmed death-ligand 1 (PD-L1) pathways may improve anti-tumor responses compared with monotherapy." (PMID 38451273, 2024). "Moreover, we established a tumor-bearing model model by subcutaneously injecting 4T1-CD155mock or 4T1-CD155KD cells to verify the antitumor efects of targeting TIGIT/CD155 signalling in vivo." (PMID 38216949, 2024). "TIGIT is highly expressed on immunosuppressive regulatory T cells (Tregs) and natural killer (NK) cells, stimulating production of the anti-inflammatory cytokine IL-10 and downregulating tumor surveillance." (PMID 39105820, 2024). "TIGIT inhibition increased CD56dim NK cell activation in response to the OC tumor." (PMID 38229100, 2024). "In both CT26- and MC38-beared mouse models, blocking TIGIT significantly suppressed tumor growth." (PMID 38543173, 2024). "Recent studies have highlighted novel associations with immune checkpoints proteins that could be useful such as LAG3, TIM3, or TIGIT due to their expression levels within tumours." (PMID 37608028, 2023). "Incomplete tumor eradication could be due to other T cell-negative regulatory pathways, such as the TIGIT/CD155 axis." (PMID 35794399, 2023). "Fusobacterium may promote tumor proliferation through Fap2, T cell immunoglobulin, and TIGIT, and inhibit the cytotoxicity of NK cells." (PMID 36860568, 2023). "In our cohort, we found an upregulation of Tim-3 at resistance in the tumor specimen of patient #6, while TIGIT upregulation was found at resistance in patients #3 and #7, suggesting that in these patients, new resistance mechanisms involving these immune checkpoints, occur." (PMID 37620318, 2023). "We first sought to determine whether TIGIT expression in lymphocytes was elevated after RT in tumor-bearing mice." (PMID 35794399, 2023). "For instance, the simultaneous inhibition of TIGIT and PD-L1 synergized to enhance tumor-infiltrating CD8+ T lymphocyte functions and promoted the rejection of transplanted tumors both in a colon cancer xenograft mouse model and in a syngeneic murine model of breast carcinoma." (PMID 37629138, 2023).
tumor (continued). "Third, the TIGIT on the surface of tumor-infiltrating CD8+T cells competitively binds to the PVR on the surface of tumor cells or dendritic cells, resulting in the failure of T cell-activated receptor CD226 to bind to PVR, thus inhibiting the activity of T cells." (PMID 37035135, 2023). "In contrast to our findings, the functional performance of TIGIT+ NK cells was reported to be lower as compared to TIGIT−, although most of the studies examined NK cells derived from tumor-bearing mice or patients either with chronic infection or cancer, which were likely already exhausted." (PMID 37345049, 2023). "Moreover, we also evaluated the in vivo specificity of the Nbs in human TIGIT knock-in mice and the ability to image TIGIT in tumor bearing mice." (PMID 37799715, 2023). "Fusobacterium nucleatum could suppress anti-tumor immunity by directly interacting with the inhibitory T-cell receptor TIGIT via FAP2 and inhibiting natural killer (NK) cell-mediated tumor killing." (PMID 37447263, 2023). "Reduced expression of TIGIT on Th2 cells promoted Th2 cell function to promote anti-tumor effects." (PMID 36913356, 2023). "Interestingly, a complete response (CR) of the primary CT26 tumor was observed in 2 of 8 (25%) mice given OAd-null treatment and in 4 of 8 (50%) mice given OAd-TIGIT-Fc treatment." (PMID 38016957, 2023). "Additionally, there was no longer a significant difference in IFNγ expression between PVR− or PVR+-K562 cell restimulation when anti-TIGIT antibodies were present in the initial tumor co-culture, indicating that the initial difference was TIGIT-dependent." (PMID 37345049, 2023). "More recently, the use of the anti-TIGIT blocking antibody tiragolumab, together with PD-1, blocking in colorectal cancer, turned out to be an efficient therapy able to restore the functionality of tumor-infiltrating CD8+ T cells." (PMID 37629138, 2023). "Therefore, treatment with anti-TIGIT mAbs can mediate the direct killing of tumor cells in patient tumor samples and preclinical mouse models and can also kill Tregs via Fc receptors (FCRs)." (PMID 36793048, 2023). "Adoptive transfer experiments using TIGIT−/− Tregs exhibited tumor inhibition and enhanced pro-inflammatory cytokine production by CD8+ tumor-infiltrating lymphocytes (TILs), which confirmed that TIGIT inhibits anti-tumor immunity predominantly by regulating Treg function." (PMID 37182149, 2023). "Notably, both TIGIT and CD96 are significantly up-regulated on NK and T cells that are chronically stimulated by tumor cells, and their expression is a hallmark of poor prognosis and resistance to chemotherapy." (PMID 37629138, 2023). "Furthermore, antibodies that specifically target NK cell inhibitory receptors, like those that target KIRs, NKG2A, and TIGIT, can boost NK cell responses and subsequently kill tumor cells." (PMID 38057843, 2023). "Unfortunately, anti-TIGIT therapy alone has been found to be insufficient for tumor control, researchers speculate that combination therapy could achieve better therapeutic outcomes in a mouse model." (PMID 35794399, 2023). "Besides, MCL tumor cells also increased TIGIT expression and then led to weaker antitumor immune surveillance." (PMID 37149643, 2023). "Furthermore, the CD39 encoding gene ENTPD1 is among the most highly upregulated genes in CD8+ T cells isolated from tumor tissue, along with other T cell exhaustion marker encoding genes (HAVCR2, CTLA4, TIGIT)." (PMID 37648263, 2023). "Several preclinical studies have demonstrated that targeting LAG-3, TIM-3, or TIGIT restores T cell function and inhibits tumor progression, and most studies indicated that coinhibition of different ICPs may effectively enhance antitumor activity." (PMID 37670328, 2023).
tumor (continued). "The observed functional activity of NK cells within the tumour was reduced, reflecting a dominant inhibitory phenotype, also accompanied by enrichment for PD-1+ TIGIT+ NK cells and a reduction in CD16, a receptor capable to bind the antibody Fc fragment, thus enabling NK cells to perform ADCC." (PMID 36980527, 2023). "Interestingly, TIGIT and CD155 were highly co-expressed in tumor compartments but showed subtle differences, TIGIT was located in the intraluminal membranes, and CD155 was expressed in the extraluminal membranes of pancreatic duct cells." (PMID 37649613, 2023). "Moreover, the interaction of CD155 on tumor cells and TIGIT on Treg further hampers the normal immune response." (PMID 37345111, 2023). "TIGIT is mainly expressed in tumor infiltrating lymphocytes, while a cell line with tumor cells overexpressed TIGIT was used in our study which may not reflect the true situation of the TME." (PMID 37129788, 2023). "Meanwhile, the emergence of RUNX1 mutation, upregulations of genes expression (RPS27A, RPS6, UBA52, RACK1) on tumor cells, and increased frequencies of T and NK cells with TIGIT, CTLA4, and LAG3 expression were observed after midostaurin treatment, predicting the disease progression of this patient." (PMID 37638009, 2023). "In addition to T cells, TIGIT can modulate anti-tumor immune responses by influencing other immune cells." (PMID 35770416, 2023). "Our findings helped identify a novel modality for this class of antibodies, prompting us to reconsider the definition of a checkpoint and how TIGIT might function in immune evasion and tumor progression." (PMID 38022590, 2023). "Anti-TIGIT antibodies have the potential to improve the efficacy of PM21-NK cell tumor immunity, and adoptive PM21-NK cells and anti-TIGIT antibodies should be explored in future preclinical studies and clinical trials as a combination therapy against lung tumors." (PMID 37345049, 2023). "Activated TIGIT+ NK cells have a better anti-tumor response as compared to TIGIT− NK cells." (PMID 37345049, 2023). "We here set out to review the literature of the past 20 years on the reciprocal interaction of TIGIT and the T cell metabolism, how it affects anti-tumor immunity, and how a better understanding of this interaction can pave the way for improved immunotherapy to treat cancer." (PMID 36874131, 2023). "Despite the increased PD1 levels, an improved PD1+CD28+ T-cell polyfunctionality was observed with the transition from periphery to tumor site, associated with lack of TIGIT, TIM-3 and LAG-3, but not with Ag-experienced-marker CD11a." (PMID 37898752, 2023). "Co-inhibition of TIGIT and PD-1/PD-L1 could synergistically elicit tumor rejection and has been approved in clinical trials, offering a new option for cancer immunotherapy." (PMID 37291608, 2023). "However, the exist of CD96 and TIGIT significantly inhibit the anti-tumor immune response of T cells." (PMID 37312116, 2023). "Aberrant TIGIT expression was observed in the cytoplasm of tumor cells." (PMID 37573372, 2023). "TIGIT was expressed on less than 20% of NK cells across all samples, showing little expression variation between tumour and blood-derived cells and was highest on tumour-infiltrating NK cells with a terminally differentiated phenotype (c6)." (PMID 37596248, 2023). "TIGIT is an inhibitory receptor expressed on lymphocytes that blocks cell cycle progression at multiple steps and has received attention in recent years as a recent target for tumor immunotherapy." (PMID 38017516, 2023). "We speculated that the ligands of NPC tumor cells may bind to various inhibitory receptors of NK cells, such as TIGIT, LAG3 and TIM-3, and reduce the cytotoxicity of NK cells." (PMID 37098551, 2023). "Furthermore, lower levels of PD1 + TIM3 + T/T/T, TIGIT + T/T, and IL-6 in the tumor microenvironment correlated with a potentially higher DCR, suggesting that patients have better clinical and survival benefits." (PMID 38110467, 2023).
tumor (continued). "Importantly, the number of IDO+ cells correlated with the number of TIGIT+ cells in tumor cores and full tumor sections." (PMID 36874131, 2023). "Notably, the frequency of CD226 expression on TIGIT + T cells was >2-fold lower in cells from tumours compared to those from blood." (PMID 37596248, 2023). "This may be explained in part by their high affinity for PD-L1 on tumor cells but low to medium affinity for TIGIT and LAG-3 on T cells." (PMID 37332070, 2023). "While TIGIT and PD-1 combined blockade had a synergistic effect in improving tumor control and survival in mouse models and early clinical trials, in a B16 mouse model the therapeutic efficacy of PD-1 and TIGIT blockade depended on the presence of NK cells, as NK cell depletion abolished the effect." (PMID 37345049, 2023). "Studies performed in vitro with human cells and in vivo preclinical models suggest that FcγR binding induces activation of NK cells and antigen-presenting cells and depletes TIGIT-expressing Treg cells and tumor cells through direct antibody-dependent cell-mediated cytotoxicity." (PMID 36512425, 2023). "Besides, TIGIT was significantly lowest expressed in T1 than T2 to T4, and significantly higher expressed in N1 than N0, in M1 than M0, which showed the significant role of TIGIT in the tumor metastasis." (PMID 37035135, 2023). "Furthermore, scRNA-seq analysis revealed that CD47 was substantially expressed in tumor cells, and we discovered that riskscore were positively linked with CD47, PDCD1, TIGIT, and LAG3." (PMID 37021054, 2023). "Our observation that TIGIT inhibition can increase TCR signaling in expanded CD8 clonotypes suggests that tumor antigen-specific T cells could potentially be reinvigorated with treatment." (PMID 38008725, 2023). "TIGIT+ Tregs acquired both highly activated and suppressed phenotypes in tumor tissues." (PMID 37670328, 2023). "As crucial immune checkpoint molecules, T-cell inhibitory receptors, including CTLA-4, PD-1, TIM-3, LAG-3, and TIGIT, are essential in limiting immunopathology and terminating effective immune response, while they can also inhibit effective anti-tumor immunity." (PMID 37056782, 2023). "Nevertheless, dual PD-1 and TIGIT engagement within the tumor will substantially impair functional responses and that this may be partially overcome by checkpoint blockade." (PMID 36689623, 2023). "In addition, we discovered that FOXP3 and TIGIT are expressed at higher levels in HNSCC patients by analyzing the TCGA tumor bulk dataset." (PMID 38096229, 2023). "Furthermore, upregulation of TIGIT is observed in tumor infiltrating T cells, and TIGIT blockade improved T cell responses." (PMID 37056774, 2023). "Furthermore, the combination of EZH2 inhibitor and TIGIT monoclonal antibody blockade enhanced the anti-tumor effect of natural killer cells." (PMID 37239949, 2023). "In a mouse model, the study blocked TIGIT, leading to f slowing of ovarian cancer tumor growth.These studies could provide new perspectives for further immunological studies and immunotherapy of relevant tumors." (PMID 37180158, 2023). "However, chronic TIGIT engagement with its ligands in the tumor microenvironment leads to the functional decline of NK cells, which can be prevented with anti-TIGIT." (PMID 37345049, 2023). "TIGIT may prevent NK cells from releasing tumor antigens, impair DC-primed T cell priming, or inhibit CD8+T cell-mediated cancer cell killing (Harjunpää and Guillerey, 2020)." (PMID 37187896, 2023). "TIGIT signaling regulates the tumor immunity cycle in multiple steps." (PMID 37345049, 2023). "Simultaneous blockade of TIGIT and PD-L1 has elicited tumor rejection and antigen-specific protection in CT-26 tumor-bearing mice, and TIM-3 has been implicated in inhibiting the cytotoxic function of Vδ2 T cells by suppressing the release of granzyme B and perforin." (PMID 38077396, 2023).